EGFR (epidermal growth factor receptor)
Diseases named in the same sentence as EGFR in open-access papers (continued):
Sharing a sentence is not in itself a finding about the gene and the disease.
cancer (continued). "Here, we demonstrate the utility of intensely blue-luminescent, small, and cationic SPION@bPEI in dye-free optical detection and therapeutic gene transfection as well as its targeted delivery to epidermal growth factor receptor (EGFR)-positive cancer cell lines, in vitro." (PMID 35116215, 2022). "The epidermal growth factor receptor (EGFR) gene is a classical target for cancer therapy." (PMID 35014769, 2022). "The discovery of orally available small molecules able to impair the EGFR activation targeting the extracellular domain could be of great interest for cancer treatment." (PMID 35954311, 2022). "Moreover, in MCF-7R cells, GPER/EGFR/ERK signaling upregulates β1-integrin expression and activates downstream kinases, which contributes to cancer-associated fibroblast-induced cell migration and the epithelial-mesenchymal transition." (PMID 36558071, 2022). "EGFR-mut cancers conserved 2 members of the SLC6 family which transport dopamine." (PMID 36612014, 2022). "Advances in targeted therapy of malignant lung tumors have been led by the development of epidermal growth factor receptor tyrosine kinase inhibitors (EGFR-TKIs) which are widely applied in the clinic as the standard first-line option for treating EGFR-mutant NSCLC with category 1 recommendations." (PMID 35673583, 2022). "Molecular targeting using antibody technology in particular is well established in both preclinical and clinical settings, with many antibodies already approved by the FDA for cancer immunotherapy such as the anti-epidermal growth factor receptor (anti-EGFR) antibody." (PMID 36243718, 2022). "In conclusion, we speculated that synthetic derivatives bear potential for cancer treatment, especially as EGFR inhibitors." (PMID 35409325, 2022). "However, treatment response is always achieved only in patients with cancer with high EGFR expression." (PMID 35903247, 2022). "The effect of sorafenib, bevacizumab, panitumumab, ramucirumab, sorafenib-bevacizumab, sorafenib-panitumumab and sorafenib-ramucirumab on the relative gene expression of CASPASE3, MMP-9, VEGFR2 and EGFR in HepG2 cancer cells was determined by RT-PCR using GAPDH as a normalizer." (PMID 36284117, 2022). "In addition, the involvement of EGFR signaling in EMT has been reported in cancer progression and metastasis." (PMID 34897389, 2022). "This is consistent with increased risk of KRAS-mut, and NEK tumors associated with smoking while EGFR-mut cancers are frequently observed in non-smokers." (PMID 36612014, 2022). "Our results suggest that when resistance to cancer treatments targeting Ras signaling arises, the observed re-activation of Ras may have been due to an increase in the levels of the EphA2 / EGFR / Ephexin1 complex." (PMID 35668076, 2022). "EGFR, human epidermal growth factor receptor 2 (HER2) and HER3 are frequently overexpressed in human cancers and have been shown to induce canonical cancer-associated signals upon their activation by mutation, gene amplification or constitutive ligand presentation." (PMID 35249128, 2022). "Furthermore, kinase-independent EGFR signaling was found to rescue cancer cells from autophagic cell death by maintaining intracellular glucose levels using sodium/glucose cotransporter 1 (SGLT1)." (PMID 35978801, 2022). "Similarly, aberrant induction of the EGFR–STAT-3–Bcl-xL signaling axis has been observed to fuel cancer progression." (PMID 35402265, 2022). "In addition, the EGFR-TKI-induced phenotype of stem cell-like cancer cells enhances the invasion and migration abilities of drug-resistant cells." (PMID 35301287, 2022). "“Confidence” value for “pemetrexed” is significantly lower than the top four, reflecting that “pemetrexed” is not a targeted therapy for EGFR mutated cancers." (PMID 35907849, 2022). "The epidermal growth factor receptor (EGFR) is over-expressed in various human cancer." (PMID 35120180, 2022). "TMEM16A can also promote cancer progression by activating EGFR and CAMK signaling." (PMID 35668455, 2022).
cancer (continued). "This resulted in the emergence of PEGylated EVs targeted to EGFR-positive cancer cells." (PMID 36290464, 2022). "Inhibition of EGFR or integrin signaling sensitized cancer cells to radiolabeled minigastrin." (PMID 36045419, 2022). "Most cancers are characterized by the acquisition of profound mutations in tumor suppressor genes (Rb, PTEN, BRCA1/BRCA2) or proto-oncogenes (HER2/neu, Ras, Myc, EGFR)." (PMID 35884561, 2022). "Our results suggest that dual-targeted therapy against cancer cells and CAFs may be more effective than single-targeted therapy for patients with high expression of both EGFR and FAP." (PMID 36418422, 2022). "AKT is a classical pathway gene of EGFR and regulates cancer metabolism." (PMID 35805016, 2022). "As a coordination game, treating the EGFR-mut may simply shift the cancer to an alternate stable state." (PMID 35061724, 2022). "Emerging evidence also suggest that EGFR and its downstream signaling pathways are closely related to autophagy regulation in various cancers, and targeting EGFR-mediated autophagy is a potential strategy for cancer treatment." (PMID 35614042, 2022). "The cancer cells compensates by unleashing inhibitory feedback on EGFR signaling." (PMID 36428475, 2022). "The protein-encoding KRAS is a GTPase protein, which in cancerous cells is activated to a GTP-bound activation state by cellular transmembrane receptor signaling such as EGFR, which further activates various cancer growth and proliferation pathways such as downstream MAPK and AKT." (PMID 36358856, 2022). "As these drugs targeting the EGFR pathway are approved for cancer treatment in other cancer types, this may facilitate the clinical evaluation of combination therapy in PCa patients treated with ENZ or those that have developed ENZR." (PMID 36167836, 2022). "EGFR activates different pathways driving aberrant cell proliferation in cancer." (PMID 36009534, 2022). "We speculated that LRP-1 is at the pivotal position to coordinate both the “eHsp90α > LRP-1” autocrine signalling and the EGFR signalling to support the constitutive motility of the cancer cells under serum-free conditions." (PMID 35835845, 2022). "Numerous studies have shown that EGFR has an important role in cancer progression." (PMID 36046036, 2022). "Exhibiting synergistic effects with the alkylating agent cisplatin as well as with the selective inhibitor of epidermal growth factor receptor (EGFR) gefitinib seems to be a promising strategy for further exploration of AT-101-based treatment options in cancer." (PMID 35215257, 2022). "EGFR is a cell surface receptor that plays a critical role in cell proliferation, survival, growth and inhibition of apoptosis and when over-expressed EGFR supports cancer progression." (PMID 36233505, 2022). "For instance, the EGFR as a TAA can be a therapeutic target for cancer therapy." (PMID 36276117, 2022). "To show that the effect of sunitinib is not limited to a single target cell line and to a single antibody, we confirmed the ADCC inhibitory effect of the drug on three additional HER2 positive cancer cell lines and in assays in which trastuzumab was replaced with the anti-EGFR antibody cetuximab." (PMID 35066605, 2022). "EGFR abnormally overactivates the downstream cancer-promoting MAPK signaling pathway." (PMID 35223512, 2022). "As previously reported, and in accordance with what was observed in the METABRIC and TCGA cancer datasets, EGFR expression is downregulated in tumors as compared with the normal breasts (2.4-fold reduction, p < 0.0001 for positivity, 2.6-fold reduction, p < 0.0001 for H-score)." (PMID 35183258, 2022). "However, its abnormal activity in the pathogenesis of human cancer requires an understanding of the complex regulation of EGFR activity and downstream signaling events." (PMID 35154122, 2022).
cancer (continued). "Moreover, we showed that the level of the GalNAc glycotope in MMP-14, EGFR, αV-, β1- and β4 integrin in highly and poorly invasive cancer cells correlated positively with their invasive potential." (PMID 35028012, 2022). "Thus, we decided to examine cancer-relevant targets that are influenced by the EGFR according to the literature to explore a possible role of zinc in carcinogenesis." (PMID 35216384, 2022). "Therefore, network analysis, and predicted affinity of bioactives of cocoa towards active site residue of EGFR seems to be in concurrence with these findings and provide possible molecular modes of action of cocoa as a potential anti-cancer nutraceutical." (PMID 35421091, 2022). "Therefore, a FAM-1-FESAN probe was used to assess the free uptake of B-ASO by EGFR-overexpressing cancer cells." (PMID 36499115, 2022). "In addition to the classic EGFR signaling pathway, EGFR nuclear trafficking is involved in cancer progression through different cellular processes." (PMID 36358752, 2022). "Then, they were subjected to KEGG enrichment analysis and visualized with the help of Omicshare cloud platform online tools; these core genes are mainly distributed in “proteoglycans in cancer”, “JAK-STAT signaling pathway”, “MicroRNAs in cancer” and “EGFR tyrosine kinase inhibitor resistance”." (PMID 36588689, 2022). "After being activated by ligands, EGFR dimerizes and triggers the production of tyrosine kinase activity to activate downstream signal pathways and participate in cell proliferation, differentiation, division, survival, and cancer development." (PMID 36118276, 2022). "Following our previous study on the development of EGFR-targeted nanomedicine (NM-scFv) for the active delivery of siRNA in EGFR-positive cancers, this study focuses on the development and the quality control of a radiolabeling method to track it in in vivo conditions with nuclear imaging." (PMID 36559172, 2022). "Understanding the complex resistance mechanisms of EGFR-TKIs and developing potential strategies to combat it could be of potential interest for improving the individual therapeutic strategies for cancer." (PMID 35840984, 2022). "EGF/EGFR activation causes the detachment of SHC-binding protein 1 (SHCBP1) from SHC adapter protein 1 (SHC1), which subsequently translocates into the nucleus and promotes cancer development via multiple signaling pathways." (PMID 35013128, 2022). "Like HER2, EGFR also plays a key role in various cancer types." (PMID 36209270, 2022). "EGFR exon 19 deletion (Ex19) mutations and EGFR exon 21 L858R point mutation (Ex21) mutations are two major EGFR mutations and molecular targeted therapies, and EGFR-tyrosine kinase inhibitors (TKI) show antitumor effects against these cancers." (PMID 36085020, 2022). "Epidermal growth factor receptor (EGFR) is overexpressed in cancer cells." (PMID 35346367, 2022). "In a cancer animal model, afatinib could suppress tumorigenesis by inhibiting the EGFR pathway of macrophages." (PMID 36443704, 2022). "As the elevated EGFR, PI3K/Akt, and NF-kB activation is considered for the possible causes of developing chemoresistance/docetaxel resistance in cancer cells so USP8 silencing might also be a thinkable way to overcome docetaxel resistance for PCa." (PMID 36338727, 2022). "Two important improvements over earlier reports are (i) our SW620 observations relate to a human carcinoma line, enabling insights to the EGF pathway in cancer directly and (ii) we have spatial information concerning EGFR and EGF localization simultaneously from labelled protein and ligand." (PMID 35612280, 2022). "Moreover, since EGFR has a pivotal role in cancer progression, metastasis, and drug resistance in NSCLC, the combinational effect of SH003 and docetaxel on the EGFR signaling pathway was also examined." (PMID 35205836, 2022).
cancer (continued). "Blocking both integrin and growth factor-dependent survival pathways may be a potential strategy to overcome the resistance of TNBC cancer cells to EGFR inhibitors." (PMID 35414025, 2022). "The increased Src activity found in cancer cells can be caused by multiple factors, including an enhanced expression of Src activators, frequently found in cancer, such as integrins, EGFR, the constitutively active mutant form EGFRvIII, HER2 or ErbB2 or other RTKs." (PMID 36217026, 2022). "Hence, targeting either EGFR or EREG can significantly deprive cancer cells of stroma-conferred resistance to chemotherapeutic drugs." (PMID 36202915, 2022). "Given the nature of the EGFR pathway as an anti-cancer drug target, our results may inform the development of new therapeutic strategies to treat cancer." (PMID 35612280, 2022). "For example, EGFR is known to regulate and maintain cancer stem cells (CSC), which are distinct subpopulations in tumors with the ability to self-renew and differentiate, and which are known to be inherently radioresistant due to their enhanced DNA damage repair abilities." (PMID 35409179, 2022). "Aberrant activation of EGFR and its marked phosphorylation have been shown to increase cell proliferation, invasion, metastasis and development of resistance to various treatments in cancers, including CRC." (PMID 35194944, 2022). "EGFR is involved in several cancer developments, including NSCLC." (PMID 35402265, 2022). "EGFR inhibitors are advantageous candidates in that they are already clinically approved and additionally offer inherent anti-cancer properties; however, whether they offer better counter-therapy than other antivirals, remains to be determined." (PMID 35572196, 2022). "In addition, a significant partner of EGFR, in this case, HER2 has been reported to be overexpressed in numerous human cancers with associated drug resistance." (PMID 36550419, 2022). "Reports have proven that the serum EGFR levels are connected with aggressive cancer development." (PMID 36556276, 2022). "Despite its proven importance in clinical oncology, it remains unknown if EGFR signaling is involved in photobiology of cancer cells and therefore be a potential photosensitizing pathway for novel therapeutic development." (PMID 35203275, 2022). "Though it is well established that HMs are contributing to various types of cancer, their association with EGFR protein is not clearly understood yet." (PMID 35607306, 2022). "In the second dataset, LUSC, PIK3CA (46.5%), EGFR (7%), PDE4DIP (6.6%), KRAS (4.4%), and RELN (4.4%) were labeled with copy number gain, while CDKN2A (27.9%), LRP1B (17.4%), PTEN (9.8%), and PTPRD (9%) appeared to be the cancer genes with copy number loss." (PMID 35330454, 2022). "Given its role in cancer progression, several EGFR inhibitors (EGFRIs) have been developed in the form of monoclonal antibodies, namely cetuximab (Erbitux®) and panitumumab (Vectibix®), as well as in the form of small-molecule drugs such as erlotinib (Tarceva®) and gefitinib (Iressa®)." (PMID 36358726, 2022). "Linking these concepts and evidence together, it is apparent that ANOs, particularly ANO1, may bridge the link between EGFR signalling and calcium signalling to regulate cancer cell proliferation, migration, and invasion." (PMID 36497413, 2022).
cancer (continued). "PDGFR transmembrane region fused with GE11 (YHWYGYTPQNVI) could secrete GE11 exosomes which show a high affinity for epidermal growth factor receptor (EGFR)-overexpressing cancer cells." (PMID 36431890, 2022). "Overexpression and activation of EGFR promote cell growth and metastasis of many cancers." (PMID 36532716, 2022). "Cancers harboring epidermal growth factor receptor (EGFR) mutation always build a non-inflamed TIME." (PMID 36145516, 2022). "Scatter plots show the correlation between EGFR expression and other genes in cancer patients." (PMID 35565451, 2022). "The epidermal growth factor receptor (EGFR) is an ErbB family receptor tyrosine kinase, which was found to contribute to tumorigenesis by supporting cell survival, proliferation, motility and other processes defining cancer cells." (PMID 35216384, 2022). "Some kinases, such as EGFR, VEGFR, RAF kinases, PKC, and Aurora kinases, just to cite a few, are amplified in various cancer types and their dysregulation is associated with poor prognosis in cancers." (PMID 36186578, 2022). "As a second-generation TKI, afatinib received FDA approval to be used in targeted therapy for patients with EGFR mutation-positive cancers, but not for ESCC." (PMID 35163685, 2022). "Because pharmaceutical EGFR inhibitors are in low supply, RNA interference (RNAi) might be an appropriate technique to target EGFRvIII to destroy cancer cells in the brain while sparing healthy cells." (PMID 36654821, 2022). "The epidermal growth factor receptor (EGFR) overexpression has been detected in most cancers." (PMID 35685897, 2022). "In some cancers, such as BC, NF-κB is overexpressed; NF-κB not only is involved in the proliferation and development of BC cells but also leads to resistance to some drugs used in cancer therapy such as anti-epidermal growth factor receptor (EGFR) drugs." (PMID 35986321, 2022). "In this work, we focused on antisense oligonucleotides decorated with boron clusters (FESAN), known as B-ASOs, which have dual therapeutic potential against cancer cells—they may act as inhibitors of EGFR gene expression and boron carriers for BNCT." (PMID 36499115, 2022). "Thus, potentiating dynamin-independent uptake of EGFR can be useful in mitigating cell proliferation in cancer cells." (PMID 36010634, 2022). "EGFR is frequently upregulated in various cancers, including GBM." (PMID 35027542, 2022). "Molecular inhibition of EGFR expression in cancer cells could inhibit the epidermal growth factor that induces increased proliferation, migration, and apoptosis." (PMID 34882994, 2022). "In addition, apoptosis plays a crucial role in the response of cancer to EGFR TKIs and also pemetrexed." (PMID 35501907, 2022). "In this way, β-catenin may also drive cancer cell survival by enhancing growth factor receptor signaling, such as Epidermal Growth Factor Receptor (EGFR)." (PMID 35454818, 2022). "In follow up studies, the possibilities of combinatorial treatments of FAO together with targeting EGFR might be investigated and their therapeutic combined value will be evaluated to help improve future cancer treatment." (PMID 35448502, 2022). "Chalcones modulated the EGFR, kinases Akt, and p-Akt level in both cancer cells." (PMID 36050500, 2022). "Of note, EGFR-mut cancers conserved transporters for monocarboxylate and riboflavin." (PMID 36612014, 2022). "In addition, epidermal growth factor receptor (EGFR) overexpression enhances Survivin expression in cancer cells through the phosphoinositide 3-kinases pathway." (PMID 35578215, 2022). "EGFR, the first discovered member of the ErbB (erythroblastic leukemia viral oncogene homolog) family, has been observed to be strongly regulated in normal tissues, and is aberrantly expressed in cancers." (PMID 35326180, 2022).